INS (insulin)
Diseases named in the same sentence as INS in open-access papers (continued):
Sharing a sentence is not in itself a finding about the gene and the disease.
Hyperglycemia (continued). "In streptozotocin-induced diabetic mice, it is either in vitro bioengineering of antral gastric cells, or in vivo reprogramming of antral gastric cells with the PMN cocktail into insulin secreting organoids can reverse hyperglycemia." (PMID 36139388, 2022). "In order to compensate for this effect, pancreatic β-cells increase the secretion of insulin, which results in hyperinsulinemia observed in insulin-resistant states and that is a primary contributor to the development of T2D, in addition to hyperglycemia." (PMID 35883605, 2022). "Parenteral administration of pharmacological doses of GLP-1 is able to normalize plasma glucose by stimulating insulin secretion and simultaneously inhibiting glucagon secretion in subjects with T2D and hyperglycemia." (PMID 36313764, 2022). "As a result, the HFD/STZ-induced rats in this study exhibited hyperglycemia and impairments in insulin secretion." (PMID 36359384, 2022). "In detail, the Y strain fish were more effective at resisting hyperglycemia by secreting insulin, synthesizing TG, and via glycolysis, although the oxidation of glucose in the muscle was inferior to that of the W strain fish." (PMID 36246125, 2022). "They thus interfere with insulin action, determining a transient phase of hyperglycaemia and a prolonged pancreatic secretion of insulin and C-peptide." (PMID 36615676, 2022). "AAV-cre-mediated liver IR deletion combined with a high fat diet (HFD) induced severely insulin resistant diabetic phenotype manifesting hyperglycemia and hyperinsulinemia." (PMID 35177603, 2022). "Streptozotocin can interfere with the function of the beta cells of the islets of Langerhans, resulting in inhibition of insulin release, which in turn leads to hyperglycemia and diabetic complications like diabetic cardiomyopathy." (PMID 35509840, 2022). "It leads to persistent hyperglycemia, insufficient insulin production or the resistance of cells to insulin action." (PMID 36080148, 2022). "In turn, vascular endothelial cells are particularly sensitive to hyperglycemia since they transport glucose in an insulin-independent manner, and intracellular glucose concentration is proportional to its blood concentration." (PMID 35890109, 2022). "The treatment of hyperglycemia in patients with GDM includes insulin, as well as oral medications, including metformin and glyburide." (PMID 36077491, 2022). "In recent decades, the plants are known as most esteemed source of novel therapeutic options as their bioactive phytocompounds exert insulin mimetic effects to counteract the hyperglycemia." (PMID 36387342, 2022). "When the body is unable to make or utilize insulin properly, blood glucose levels rise (known as hyperglycaemia)." (PMID 35875742, 2022). "Hyperglycemia, insulin resistance, hyperinsulinemia, and impaired metabolic signaling of insulin are all involved in the pathogenesis of diabetic cardiomyopathy and induce a series of pathophysiological phenomena." (PMID 35204091, 2022). "Haplodeficiency Klotho has been related to hyperglycemia, glucose intolerance, reduced insulin deposits and β -pancreatic apoptosis." (PMID 35055149, 2022). "The first is associated with Cushingoid obesity with fluctuation between documented hypo- and hyperglycemia, resulting in over- and underdosing of insulin treatment." (PMID 35655318, 2022). "Type 1 diabetes (T1D) is characterized by autoimmune-driven destruction of insulin-producing β-cells, which leads to altered control of glucose homeostasis and induction of hyperglycemia." (PMID 36090775, 2022). "Currently, there are many antidiabetic drugs available in the market to treat hyperglycemia which notably works via improvement of insulin sensitivity, complementing insulin, upraising insulin secretion and stimulating glucose uptake." (PMID 35282429, 2022). "Insulin appears to be able to counteract the pro-oxidant effects of ambient hyperglycemia and glycemic fluctuation by inhibiting the activation of oxidative stress." (PMID 36211422, 2022).
Hyperglycemia (continued). "Insulin administration is the preferred way to control hyperglycemia in hospitalized patients with a starting threshold below 180 mg/dl." (PMID 36619546, 2022). "In another controlled study with fasting only (insulin given only for hyperglycemia), a 48% reduction after 24 h was achieved, compared to 71% in the PE group." (PMID 35492338, 2022). "The STAM model is characterized by hyperglycemia and reduced body weight with reduced Gck expression, which is exclusively regulated by insulin signaling." (PMID 35203369, 2022). "It is typically characterized by chronic hyperglycemia, hyperinsulinemia, dyslipidemia, and lipotoxicity, resulting in progressive deterioration of insulin secretion and insulin action." (PMID 36324618, 2022). "At 28 days of age, basal hyperglycemia, IR, and impaired insulin secretion by pancreatic beta-cells are observed." (PMID 35648976, 2022). "The patient presented with growth retardation, peculiar facial features, acanthosis nigricans, hypertrichosis, extremely high insulin levels, fasting hypoglycemia, and postprandial hyperglycemia." (PMID 36626508, 2022). "Consumption of whey protein half-hour before a carbohydrate meal, resulted in reduced postprandial hyperglycemia and increased plasma insulin levels." (PMID 35215472, 2022). "Short- and long-term clinical trials in subjects with T2DM suggested that consuming more lower fat containing proteins than carbohydrates at breakfast help to reduce postprandial hyperglycemia, insulin responses and blood lipids." (PMID 35215472, 2022). "T1DM, also known as autoimmune diabetes mellitus, is characterized by irreversible destruction of insulin-producing β-cells in pancreatic islets and an absolute paucity of endogenous insulin with subsequent hyperglycemia." (PMID 35979435, 2022). "Functional tests are able to detect an impairment of insulin production and dysregulation of glucose metabolism in the preclinical phase, however specific signs or symptoms are only shown with manifest hyperglycemia, the clinical stage." (PMID 35844538, 2022). "The polyol pathway is activated by hyperglycaemia, especially in non-insulin target tissues, including the kidneys." (PMID 36499723, 2022). "During the re-induction, hyperglycemia (serum glucose 14.5 mmol/L) appeared the third day of dexamethasone use (10 mg/m2/day), necessitating multiple daily insulin injections (basal-bolus regimen) for 34 days." (PMID 35399095, 2022). "When compared to the HFD therapy, the findings showed that GP peptides dramatically reduced fasting hyperglycemia, insulin secretion, and proinflammatory markers." (PMID 36062167, 2022). "First, the combination of GLP-1 RAs with basal insulin targets both fasting and, more importantly, postprandial hyperglycemia." (PMID 36559020, 2022). "A parallel double-blind randomized clinical trial including hospitalized patients with SARS-CoV-2 infection and hyperglycemia, randomized to receive 5 mg linagliptin + insulin (LI group) or insulin alone (I group) was performed." (PMID 35017617, 2022). "When treating patients with marked hyperglycemia requiring hospitalization, fortified insulin therapy or continuous intravenous insulin therapy is often the treatment of choice." (PMID 35574023, 2022). "Two of the earliest closed-loop systems – those developed by Kadish and Shichiri – utilized a dual-hormone approach with a combination of insulin to counter hyperglycemia and glucagon to counter hypoglycemia." (PMID 35733769, 2022). "In aldh3a1 knockout zebrafish mutants, increased 4-HNE concentrations disrupted the pancreas formation, which inhibited insulin expression and thereby facilitated hyperglycemia and a retinal vasodilatory phenotype." (PMID 35114580, 2022). "GLUT2 dysfunction in the liver can lead to hyperglycemia due to decreased response and sensitivity of hepatocytes to insulin signaling, resulting in reduced inhibition of glucose production." (PMID 35757134, 2022).
Hyperglycemia (continued). "Analysis of the model simulations indicate that HepaRG/HHSteC spheroids exposed to normoglycemic conditions over the co-culture period exhibited higher insulin sensitivities than those maintained under hyperglycemia." (PMID 36260620, 2022). "T2DM is a heterogeneous metabolic disorder, characterized by insulin tolerance and cell dysfunction, resulting in persistent hyperglycemia." (PMID 35807304, 2022). "This initially led to the treatment of spurious hyperglycemia with high-dose insulin and a delayed correct diagnosis and treatment, rendering substantial risk for the patient." (PMID 36196332, 2022). "Despite only achieving partial adipose tissue depot development when compared with WT controls, this was sufficient to normalize hyperglycemia, decrease serum TGs, reduce hepatomegaly, and restore insulin sensitivity." (PMID 36320417, 2022). "For instance, selenite can alleviate hyperglycemia via serving as an insulin mimic, whereas selenite inhibit insulin signaling in diabetic mice." (PMID 36312938, 2022). "In fact, a sedentary lifestyle is associated with increased oxidative stress and metabolic dysfunction that can result in hyperglycemia, reduced insulin sensitivity, hypertriglyceridemia, and hypertension, all of which increase CV risk." (PMID 36703856, 2022). "The insufficient compensatory increase in insulin secretion is noted, which leads to hyperglycaemia under the conditions of a greater decrease in insulin sensitivity than in normal pregnancy." (PMID 35163753, 2022). "This study showed that C. speciosus significantly reduced STZ-induced hyperglycemia and significantly increased serum insulin in diabetic rats in a comparable level to that of metformin." (PMID 35164292, 2022). "Under hyperglycemia, excessive glucose increased ROS production, which promoted pore formation on ER membranes, allowing the release of INS." (PMID 36296745, 2022). "We identified other potentially effective pharmacologic treatments, notably sulfonylureas or insulin, that relieve hyperglycemia by increasing insulin levels." (PMID 35212193, 2022). "The resulting organoids displayed reduced hypoxic stress, increased insulin secretion in vitro and faster hyperglycemia-reversing ability due to rapid revascularization compared to non-pre-vascularized organoids and fresh islets." (PMID 36090775, 2022). "Anthocyanins (ANT) are polyphenolic compounds present in various food and play an important role in ameliorating hyperglycemia and insulin sensitivity." (PMID 36335368, 2022). "Insulin is only recommended for difficult-to-manage grade ≥3 hyperglycemia, since insulin activates the PI3K pathway and has been shown to induce breast cancer cell proliferation in vitro." (PMID 35016012, 2022). "Conversely, hyperglycemia (blood glucose ≥10.0 mmol/L) is also a common observation during the first postnatal weeks due to a combination of insulin resistance, pancreatic β-cell immaturity and parenteral nutrient infusion." (PMID 35989990, 2022). "NS is also reported to reduce hyperglycemia in streptozotocin-induced diabetic rat models, upregulation of serum insulin expression, regeneration of pancreatic beta cells, and increased insulin in immunoreactive β-cells." (PMID 36354542, 2022). "Postprandial, insulin prevents hyperglycemia, suppressing hepatic glycogenolysis and gluconeogenesis." (PMID 35204293, 2022). "Under diabetic conditions, when β-cells are chronically exposed to hyperglycemia, β-cell function gradually deteriorates, which progressively reduces insulin biosynthesis and secretion." (PMID 35918386, 2022). "The incidence of adverse events, including hyperglycemia (requiring insulin infusion), pulmonary and systemic infections, and gastrointestinal bleeding, was low." (PMID 36190994, 2022). "The dietary intervention of KAA, such as leucine, produced an improved insulin function, decreased hyperglycemia, and hypercholesterolemia in high-fat diet-induced obesity models." (PMID 35159714, 2022).
Hyperglycemia (continued). "In an obese mouse model, overexpression of FNDC5 enhances energy expenditure, lipolysis, and insulin sensitivity, and improves hyperlipidemia, hyperglycemia, and hyperinsulinemia." (PMID 36004352, 2022). "The finding suggested that the function of insulin secretion of DM mice has been affected by continued hyperglycemia." (PMID 36080407, 2022). "Insulin, its variates, and other therapeutic molecules which can modulate hyperglycemia have already been extensively delivered using nanoparticles to remediate the condition." (PMID 35336018, 2022). "Metformin reduces hyperglycemia, suppresses hepatic gluconeogenesis, and increases insulin sensitivity." (PMID 35629267, 2022). "Of note, we found that the mice developed hyperglycaemia because of a reduction in the plasma insulin level under a high fat diet (HFD)-feeding." (PMID 35614067, 2022). "In our previous publication, we found that intervention with oral antidiabetic medication at the time of insulin discontinuation or near-normoglycemia remission predicted longer hyperglycemia relapse-free survival." (PMID 35721763, 2022). "Among adults using insulin, we found that racial and ethnic minority patients, uninsured patients, and those with low family income had the highest levels of severe hyperglycemia." (PMID 36538330, 2022). "Hybrid closed-loop systems aim to minimize hypoglycemia and hyperglycemia and maintain glucose levels within a target range through the use of a computerized algorithm to adjust the basal rate of insulin and administer corrective bolus doses." (PMID 35733769, 2022). "When the BGL rises (hyperglycemia), GOx will catalyze the conversion of glucose to gluconic acid and H2O2, which causes the rapid rupture of the ERs, creating pores and releasing INS (the “on” state)." (PMID 36296745, 2022). "Exogenous insulin is sometimes given to control hyperglycemia, but its use is controversial as it is generally ineffective at controlling hyperglycemia and insulin use is associated with increased mortality and ROP." (PMID 36420952, 2022). "Decreased insulin sensitivity and increased glucose production lead to decreased islet cell function and hyperglycemia, as well as increased release of inflammatory factors (such as IL-6, TNF-α, and C-reactive protein)." (PMID 35432188, 2022). "Specifically, 1-h PG ≥199 mg/dl at the time of insulin discontinuation, even after adjustment for age, BMI, gender, presentation with DKA or SH, and HbA1c levels, was independently associated with hyperglycemia relapse." (PMID 35721763, 2022). "Pooling data from these trials showed positive and significant effects of probiotics in the reduction of hyperglycemia, insulin concentration levels, lipid profile, and BMI (Body mass index)." (PMID 36160290, 2022). "Compared with insulin, metformin is able to attain target glucose levels faster at treatment initiation, lowering fetal exposure to hyperglycemia." (PMID 35745174, 2022). "It is used in the treatment of T2DM and has already proved to be effective in improving insulin sensitivity, hyperglycemia, and lipid metabolism." (PMID 35176115, 2022). "Patients with stress hyperglycemia had significantly higher plasma insulin, HOMA-index, TyG index, and lactate dehydrogenase and lower total and LDL-cholesterol levels than patients without stress hyperglycemia." (PMID 36059840, 2022). "GAWE extract containing various phenolic compounds such as quercetin 7-O-glucoside, apigenin 7-O-glucoside, and vanillic acid regenerates pancreas β-cell, and therefore increased insulin secretion, and prevented hyperglycemia." (PMID 36082185, 2022). "The inability to produce or use insulin in the cells results in a high sudden surge of glucose levels in the bloodstream, called postprandial hyperglycemia." (PMID 35057448, 2022).
Hyperglycemia (continued). "In pregnant rats fed with the HFHS diet, a single low-dose intraperitoneal injection of STZ can mildly impair the insulin secretion function of pancreatic islet β cells and effectively induce hyperglycemia and form pathogenesis similar to GDM." (PMID 36107823, 2022). "Meanwhile, insulin stimulates muscle and adipocyte glucose uptake under conditions of hyperglycemia (the stimulus for insulin release from β-cells), and promotes glycogen and triglyceride storage." (PMID 35736456, 2022). "The introduction of insulin reflects clinically meaningful hyperglycaemia and is measured at any time during the clinical trial." (PMID 36131291, 2022). "They decrease oxidative stress and reduce inflammation, reduce and prevent atherosclerotic, atherothrombotic, and arteriosclerotic processes, and improve blood pressure, lipid profile, hyperglycemia, and peripheral insulin sensitivity." (PMID 36364796, 2022). "Sensitivity analysis confirmed that patients on insulin or oral hypoglycemic agents had a more blunted response to hyperglycemia, and hypoglycemia, and were less affected by glucose variability." (PMID 35842591, 2022). "As seen from the glucose dynamic results, increasing glucose levels in zebrafish larvae between 260 min and 12 h after initial insulin induction (250 nM insulin) can result in transient hyperglycemia." (PMID 35955446, 2022). "The pathogenesis of diabetic atherosclerosis involves hyperglycemia, dyslipidemia, changes in secretion of hormone other than insulin, and a proinflammatory state." (PMID 35668496, 2022). "Metformin acts on hyperglycemia by decreasing hepatic gluconeogenesis and increasing insulin sensitivity." (PMID 35562979, 2022). "It is recommended that patients continue long-acting analogue insulin therapy alongside intravenous infusions to prevent rebound hyperglycaemia after the intravenous treatment has ceased." (PMID 35274050, 2022). "DM is a metabolic disease characterized by hyperglycemia that results from improper insulin secretion and/or target tissues resistance to insulin." (PMID 35626360, 2022). "It promotes fatty acid β-oxidation by modulating the respective genes as well as improve glucose metabolism in T2DM by increasing insulin sensitivity and reducing hyperglycemia and hyperinsulinemia." (PMID 35242140, 2022). "Treatment with the aqueous extract of Thymus serpyllum was found to be significantly effective in controlling hyperglycemia and improving glucose and insulin tolerance." (PMID 36079819, 2022). "Several studies revealed that ebselen lowers hyperglycemia and activates the insulin signaling pathway 21-23, but the exact molecular mechanism remained open." (PMID 35342343, 2022). "Reduced insulin-stimulated glucose uptake further contributes to hyperglycemia which overburdens the β-cell, producing an additional insulin response and worsening β-cell dysfunction." (PMID 36733795, 2022). "The hydrogel reversed hyperglycemia, gradually reducing the exogenous insulin need, and efficiently supported optimal graft revascularization." (PMID 36090775, 2022). "Patients with T1DM should receive insulin to avoid the long-term consequence of hyperglycemia and they also should be cautious to take the proper amount of insulin and prevent hypoglycemia." (PMID 36572938, 2022). "The metabolic consequences of IR are hyperglycemia, impaired insulin secretion, oxidative stress, hypertension, dyslipidemia and increased visceral fat deposition." (PMID 35562979, 2022). "Many pharmacological approaches have been used to improve hyperglycemia, mainly through stimulating insulin release, increasing glucose transport activity, inhibiting gluconeogenesis, and reducing absorption of glucose from the intestine." (PMID 35408574, 2022). "Hyperglycemia leads to the overproduction of the inflammatory cytokines, increased oxidative stress, and increased insulin resistance, leading to skeletal muscle atrophy, predominantly in fast muscles." (PMID 34997408, 2022).